CD81 (CD81 molecule)
Diseases named in the same sentence as CD81 in open-access papers (continued):
Sharing a sentence is not in itself a finding about the gene and the disease.
tumor (continued). "The findings suggest a possible link between the cytotoxic effects of these saponins on tumor cells and their interaction with CD81." (PMID 39850717, 2024). "By utilizing the SEA platform for target prediction, a common tumor related target CD81 was identified." (PMID 39850717, 2024). "Another essential partner of CD81 is the B-lymphocyte coreceptor CD19, which is a key activator of the PI3K pathway and a prominent tumor-associated antigen." (PMID 37046846, 2023). "Compared to the hOMF-Exo group, in the tumor tissues of nude mice after CAFs-Exo injection (P = 0.0015) and in Cal-27 cells co-cultured with CAFs-Exo (P = 0.0035), CD81 expression was significantly elevated." (PMID 37365497, 2023). "The suppression of CD81 with a shRNA in mesenchymal breast cancer has been shown to reduce primary tumor growth, extravasation and lung metastasis in vivo." (PMID 37046846, 2023). "NicheNet predicted multiple interactions between all tumor-infiltrating DC subsets and Tregs, however, the Cd81+migcDC1 showed the strongest evidence of actual interaction." (PMID 37622122, 2023). "Related studies reported that CD81 contributes to tumor growth, as well as tumor cell migration and invasion." (PMID 37365497, 2023). "Slightly higher level of CD81 signal corresponding to EVs isolated from recurrent ascites reveals their higher concentration in the ascitic fluid of relapsed tumor." (PMID 36875773, 2023). "CD81, in particular, is tightly regulated in physiological and pathological processes, including inflammation, pathogen infection, cell adhesion, and tumor development." (PMID 38136327, 2023). "In this study, ST results indicated that CD81 was primarily distributed in the exocrine part of the normal pancreas and in iCAFs of tumor stroma, showing an increasing trend." (PMID 37124494, 2023). "CD81 plays key roles in tumor growth and dissemination, and serves as a co-receptor for a number of viruses." (PMID 37046846, 2023). "CD81, a promoter of tumor growth and metastasis, serves as a coreceptor for viral entry and is reported in exosomes." (PMID 36437456, 2022). "Here we show that the mammosphere-promoting functions of exosomal CD44 and CD81 illustrate the crosstalk between tumor-initiating cells and surrounding cancer cells that potentially contributes to their self-renewal and/or plasticity." (PMID 36193887, 2022). "In the WT group, ~50% of adherent cells and 70% of suspension cells showed an average of 14–16% of partial colocalization between CD44 and CD81 on the cytoplasmic membrane, with CD81 mainly presented at the interface of the clustered tumor cells in suspension." (PMID 36193887, 2022). "We observed CD81 expression on different infiltrated immune subsets within the tumor, including cytotoxic and terminally exhausted CD8 T cells that expressed GPR56." (PMID 35804934, 2022). "CD81 depletion or downregulation resulted in compromised cluster formation in all four tested human and mouse TNBC models, suggesting an important role of CD81 in promoting tumor cell aggregation." (PMID 36193887, 2022). "Up to 45 days after injection, we observed compromised tumor initiation and growth in the CD81− cells, especially at the 100 cell dilution, compared to the CD81+ cells that grew tumors at both dilutions." (PMID 36193887, 2022). "(D) Distinct mouse survival between 4T1 WT and Cd81 KO tumor bearing mice with spontaneous lung metastases." (PMID 36193887, 2022). "The results of Western blot analysis also showed that exosomes secreted from 4T1 tumor cells express CD81, CD9, CD63, and TSG101 markers along which β-actin was used as the internal control." (PMID 34194604, 2021). "Although the secretion of CD81+CD63+EVs from 67NR clones caused an increase in proliferation and migration in vitro, the tumor growth was inhibited in vivo." (PMID 34503207, 2021). "We next wanted to investigate the impact of CD81+CD63+EV secretion on the functional properties of the 67NR tumor cells." (PMID 34503207, 2021).
tumor (continued). "An autopsy study in ICI myositis found CD81+ T-cell in the tumor, heart, and skeletal muscle, indicating the possible association between muscle injury and cross-reactive T cells in tumor and muscles." (PMID 34805229, 2021). "Only minor differences in overall levels of tetraspanins were observed when comparing normal with disease EVs, whereby CD9 and CD63 appeared to increase, and CD81 decreased, in tumour‐stroma EVs." (PMID 34596356, 2021). "MM BM-mesenchymal stromal cell (MSC)-derived exosomes, defined as CD63+/CD81+, promote MM tumor growth via downregulation of a tumor suppressor miR-15a; in contrast, normal BM-MSC exosomes inhibit growth of MM cells." (PMID 33435632, 2021). "Lastly, the expression of CD81 in VSCC samples was robustly correlated with tumor relapse, especially in patients who underwent neoadjuvant therapy." (PMID 34065085, 2021). "So far, this notion is supported by recent studies of the role of tetraspanins CD9 and CD81 in metabolism of glutamate and lipids in normal or tumor tissues." (PMID 33919420, 2021). "Combined in vitro and animal studies with these cell lines suggested that CD81+CD63+EV secretion can impede tumor formation." (PMID 34503207, 2021). "A series of experimental or clinical results have demonstrated that CD81 is a potential target for tumor therapy." (PMID 33919192, 2021). "Unlike the antigens such as CD20, CD19, or CD37 used to target tumor cells since they are expressed on specific tumor tissues and subpopulations, CD81 is widely expressed in both normal tissues and tumor cells." (PMID 33919192, 2021). "Further, CD81 has been found to contribute to tumor progression and an enhanced metastatic phenotype." (PMID 33669943, 2021). "Recently, it was reported that CD81 knockout mice have impaired functions of regulatory T cells in a tumour transplantation model." (PMID 32332834, 2020). "In agreement with previous reports, KLF4 mRNA expression was remarkably downregulated in tumor tissues, and lower expression of CD9 and CD81 mRNAs were observed in tumor tissues as compared with adjacent normal tissues." (PMID 32350244, 2020). "The results of subcutaneously transplanted tumor model indicated that CD9 or CD81 knockdown significantly enhanced tumorigenicity of HCC in vivo." (PMID 32350244, 2020). "Tetraspanins CD9 and CD81 frequently serve as the surface markers of exosomes, which are involved in intercellular communication during tumor progression." (PMID 32350244, 2020). "Proteins such as CD9, CD63, and CD81 are located on the exosome surface, and tumor-associated markers (HER2, EpCAM) are also present on tumor-associated exosomes." (PMID 32582658, 2020). "The results showed that both of CD9 and CD81 overexpression significantly inhibited tumor growth, which were in line with the results in vitro." (PMID 32350244, 2020). "Further statistical analysis showed that KLF4 expression was positively correlated with the expression of CD9 (r = 0.510, P < 0.01) and CD81 (r = 0.382, P < 0.05) in tumor tissues." (PMID 32350244, 2020). "Decreased expressions of CD9 and CD81 were found in most HCC tumor tissues and predicted advanced stages." (PMID 32350244, 2020). "In oncology, CD9 overexpression in tumors has been associated increased risk of invasion and development of metastasis, especially when it forms a complex with its molecular partner CD81, where it then facilitates long-term tumor growth." (PMID 31191817, 2019). "Second, when we administered purified SDCSC exosomes ectopically expressing FLAG-tagged CD81 via a tail vein injection into tumor-free mice, CD11b+/Gr-1+ neutrophils were the predominant group engulfing exogenous tumor exosomes in the bone marrow." (PMID 30683126, 2019). "We describe the conditions for detection of MICA in exosomes and prove, for the first time using both techniques, the co-existence in one vesicle of exosomal markers (the tetraspanins CD9, CD63 and CD81) and an endogenously expressed tumour-derived antigen." (PMID 29720199, 2018).
tumor (continued). "For example, we identified several members of the tetraspanins family (Tetraspanin-14, CD9, CD63, and CD81 antigens) to be increased in tumor-derived exosomes from the non-invasive cell line, MCF-7." (PMID 25798887, 2015). "The first major finding of our study is that the CD9/CD81 complex is in fact required for certain aspects of α3β1 integrin function in tumor cells." (PMID 23613949, 2013). "Our new data now establish that depletion of the CD9/CD81 complex can have a significant impact on α3β1 integrin function in tumor cells." (PMID 23613949, 2013). "Immunoblotting with the anti-CD81 antibody of these lysates showed that tumours treated with vehicle and those treated with GS-168AT2 contained equivalent amounts of CD81 at the end of the treatments." (PMID 21206492, 2011). "FAK was highly expressed in the control tumor brains as compared to hUCBSC-treated brain sections, which showed high expression of CD81." (PMID 21068464, 2010). "When antibodies specific for CXCL1, TPT1 or CD81 were added to tumor co-cultures with NPC, the suppressive effect by the NPC was significantly enhanced in several combinations of NPC and tumor, although to a varying extent." (PMID 19558675, 2009). "CD81 is a cell surface protein that plays an important part in tumor development." (PMID 41211316, 2025). "Collectively, these data suggested that CD81 was overexpressed in OC and could be the potential target for the treatment of the tumour with significant prognostic value." (PMID 40604335, 2025). "Notably, the expression of the CD81 molecule on both tumor-infiltrating CD8+ and CD4+ T cells was significantly enhanced following GCP combination therapy, emphasizing the potential role of CD81 in T-cell reactivation." (PMID 41409288, 2025). "CD81 promoted the production of PCS, which not only regulated tumour growth but also enhanced the mitophagy of T cell immunoglobulin and mucin domain containing 4 (Tim4) positive tumour‐associated macrophages (TAMs)." (PMID 40604335, 2025). "Moreover, differences in cluster counts between surface markers (CD81, EpCAM, PD-L1) and the intravesicular marker Cyclin D1 also correlated with tumor stage." (PMID 41008614, 2025). "CD81-positive sEVs mediate viral immune evasion and promote tumor progression in HCV-associated HCC; HCV viral particles exploit CD81-positive sEVs for transmission, and this sEVs subpopulation is significantly enriched in HCV-positive HCC patients, suggesting its potential as a therapeutic target." (PMID 40703510, 2025). "Several studies have focused on anti‐CD81 antibodies treatment concerning tumour progression and metastasis, and therapies targeting CD81 could be developed for future cancer treatment." (PMID 40604335, 2025). "Furthermore, there was an observable reduction of tumour volume after knocking down CD81 expression of OC cells in making a subcutaneous tumour model." (PMID 40604335, 2025). "We speculate that when CD81 is combined with a specific marker of AMKL tumor cells, such as CD41 or CD61, as a target of a therapy such as CAR-T, it may be possible to specifically eliminate AMKL tumor cells." (PMID 41211316, 2025). "Furthermore, we purified Tim4+ TAMs from the peritoneal metastasis tumour models (NC and sh‐CD81 groups) for RNA sequencing." (PMID 40604335, 2025). "Overall, it hinted that PCS might be the key mediator to transfer information between OC cells and Tim4+ TAMs through CD81 signalling, but the effect of tumour‐derived PCS on Tim4+ TAMs under CD81 signalling need to explore." (PMID 40604335, 2025). "Elimination of CD81 inhibited tumor growth and metastasis by immunomodulation." (PMID 37365497, 2023). "Interestingly, we observed that the exosomes derived from A549-Linc01703 decreased the infiltration of CD86+ B cells in the tumor microenvironment, while CD81 silencing reversed it." (PMID 38136327, 2023). "In cancer, the knockout of CD81 was shown to reduce tumor formation and metastasis." (PMID 37046846, 2023).
tumor (continued). "According to this network, we found that the exosome markers CD81, CD9, CD63, and TSG101 were associated with ANXA9, suggesting that ANXA9 may exist in exosomes in tumor tissues." (PMID 37294149, 2023). "Similarly, in our study, we found that CD81, which is abundant in the exosome derived from A549-Linc01703 cells, can be secreted and play a biological role in the tumor microenvironment." (PMID 38136327, 2023). "We think that the increased release of CD9 and CD81-positive EVs might provide a promising marker to monitor GBM tumor response to radiotherapy." (PMID 36203458, 2022). "Our study found seven downstream factors that may be associated with chemoresistance, LTF, SOD2, STAT1, CDKN2A, CD81, RAC1, and NDRG1 and five factors that may be associated with tumor development, CCN1, DCTN3, MUC1, H1-5, and SLC1A5." (PMID 35421932, 2022). "In addition, exosome-specific markers TSG101, CD9, CD63 and CD81 were evaluated in tumor-derived exosomes through different methodologies." (PMID 35804987, 2022). "This work aims to determine the role of CD81 in EVs, tumor initiation, and metastasis." (PMID 36193887, 2022). "In conclusion, Ecad+ EVs and CD45+ EVs, respectively, derived from epithelial cells and immune cells, constituted a minor fraction (11%) of thyroid tissue-derived CD9+/CD81+ EV pool, but showed a doubling in their proportion within the total EV pool of tumor tissue (23%)." (PMID 35453506, 2022). "Exosomes play an important role for tumor development and could be used as biomarkers detected by QD-conjugates together with anti-exosome magnetic beads (e.g., anti-CD81), as shown for HER2-positive patient-derived exosomes." (PMID 36291832, 2022). "CD81, a promoter of tumor growth and metastasis, serves as a co-receptor for viral entry." (PMID 36437456, 2022). "The positive correlation and interaction between IFITM1 and CD81 potentially expands the effect of IFITM1 on antitumor immunity, as CD81 plays an important role in the activities of tumor-infiltrating immunosuppressive cells (MDSCs and regulatory T cells (Tregs))." (PMID 36466909, 2022). "Generally, immuno‐based microfluidic and microarray technologies have utilised tetraspanins (CD9, CD81 and CD63) and tumour‐cell surface associated markers such as EpCAM, CA125, CD19, EGFR, EGFRvIII, podoplanin and PDGFR for on‐chip capture of tumour‐EV sub‐populations." (PMID 36239734, 2022). "These bioinformatic analyses indicate that CD81 may serve as a candidate biomarker of tumor radioresistance and therapeutic outcome." (PMID 33919192, 2021). "Moreover, colonosphere-derived EVs containing FLAG-tagged CD81 were intravenously injected into tumor-free mice and CD11b+/Gr-1+ neutrophils were identified as the predominant group engulfing exogenous tumor EVs in the bone marrow." (PMID 33946403, 2021). "According to our findings, since CD81 promotes Rad51-dependent DNA repair and thus acts as an intrinsic factor of tumor radioresistance, we speculate that combination of radiotherapy and CD81 inhibitor may promote therapeutic effect by attenuating HRR in GBM." (PMID 33919192, 2021). "Moreover, we found that the expression level of CD81 was positively correlated with Pax5 expression in human tumor cell lines." (PMID 34824296, 2021). "Both normal and tumour‐associated EVs were strongly positive for CD9, CD81 and CD63." (PMID 34596356, 2021). "The effective isolation of EVs was confirmed by western blot analysis, with positive signal for the tetraspanins CD9, CD63, CD81 and Tumour Susceptibility Gene 101 (TSG101), while negative for the cellular marker calnexin." (PMID 33216826, 2020).
tumor (continued). "Moreover, to confirm these findings in vivo, CD9- or CD81-overexpressed Huh7 cells were used to establish a subcutaneous xenotransplanted tumor model in nude mice." (PMID 32350244, 2020). "Collectively, these observations implied that CD9 and CD81 may function as tumor suppressors in HCC." (PMID 32350244, 2020). "We detected Tspan8, CD9, and CD81 signals on EVs isolated in control and in tumour‐bearing animals." (PMID 30982971, 2019). "A tumor-free testis showed a strong membranous and cytoplasmic expression of CD81 protein (arrow)." (PMID 31565104, 2019). "Additionally, expression of CD81 in the host contributes to tumor progression; CD81KO mice have fewer metastases of breast and lung tumors in syngeneic mouse models." (PMID 29946318, 2018). "Because CD81 is a well-known marker of EVs, it is possible that CD81-positive EVs derived from other cell types within the tumor microenvironment may contribute to the activation of the Wnt-PCP pathway in cancer cells." (PMID 27582126, 2017). "Among the proteins that showed distinctive expression in the AbM profiling, 2 representative proteins, CREB-binding protein (CREBBP) and CD81, were chosen, and their prognostic significance for tumor recurrence and progression were investigated in an independent primary HG NMIBC cohort." (PMID 25915404, 2015). "Similarly, univariate Cox regression analyses showed that CREBBP and CD81 expression were significant predictors for tumor recurrence and progression." (PMID 25915404, 2015). "However, neoplastic hepatocytes in HCC expressed higher levels of CD81 and this was more marked in poorly-differentiated tumour compared to well-differentiated HCC." (PMID 24662676, 2014). "In addition, we reveal poorly differentiated HCC express significantly higher levels of CD81 compared to adjacent non-tumor tissue." (PMID 24662676, 2014). "Incubation of GS-168AT2 with the hLT cell line NCI-H460 leads to the association of GS-168AT2 with both CD9 and CD81, and treatment of NCI-H460-xenografted Nude mice with GS-168AT2 leads to a drastic inhibition of tumour growth, which is associated with the in vivo downregulation of CD9 in tumours." (PMID 21206492, 2011). "We were able to show that CD81 has a proliferative effect on tumor growth of N29 and N32." (PMID 19558675, 2009). "Beyond its direct cellular functions, CD81 also modulates the immune environment with tumour hosts to mediately involve cancer progression, such as impairing the suppressive ability of T regulatory cells (Tregs) and myeloid‐derived suppressor cells (MDSCs) in tumour‐bearing mice." (PMID 40604335, 2025). "Moreover, through RNA sequencing analysis in tumor CD8+ T cells, we found that genes associated with effector functions, such as Sox6, Ccnd1, CD81 and Trim14, were upregulated, while genes associated with immune inhibition, such as Tox, Jun-b, Btla, Batf and Foxp1 were downregulated 25-27." (PMID 38994031, 2024). "In our pilot experiment, we performed comparative analysis of CD117, EpCam and CD81 abundance on EVs isolated from ascitic fluids of the patient with primary tumor (ovarian papillary cystadenocarcinoma) and of the same patient with post-treatment tumor relapse." (PMID 36875773, 2023). "Finally, we measured the CTC events in the blood within 1 day following tail vein injection of 4T1 tumor cells and found that Cd81 KO cells (singles and clusters) were less detectable than the WT controls, in parallel with reduced seeding for lung colonization (n = 3 mice/group)." (PMID 36193887, 2022). "In-depth global and phosphoproteomic analyses of tumor cells deficient with CD81 or CD44 unveils endocytosis-related pathway alterations, leading to further identification of a quality-keeping role of CD44 and CD81 in EV secretion as well as in EV-associated stemness-promoting function." (PMID 36193887, 2022). "Importantly, expression of CD81 in immune suppressive cells contributes to tumor progression." (PMID 29946318, 2018).